IL1B (interleukin 1 beta)
Diseases named in the same sentence as IL1B in open-access papers (continued):
Sharing a sentence is not in itself a finding about the gene and the disease.
infection (continued). "We found that early processing of caspase-1, induction of pyroptosis and secretion of IL-1β were reduced after infection of BMM with a B. pseudomallei flagellin FliC mutant." (PMID 24626296, 2014). "In rVK627E infection group, the expression level of IL-1β rose from 1 dpi to 5 dpi which achieved its peak before declined to the lowest level at 6 dpi." (PMID 25547136, 2014). "In mouse models of infection, IL-1β, IL-6, and TNF-α are important protective cytokines during S. pneumoniae infection, and we have now demonstrated that expression of these cytokines by healthy controls was largely dependent on lipoproteins." (PMID 25172490, 2014). "We evaluated the levels of TNF-α, IFN-γ, IL-1β, and IL-6 in the hepatic tissue of untreated or EtOH-treated mice and uninfected or infected with Ab at 24, 48, and 72 h post-infection." (PMID 24752133, 2014). "IL-1β is also an important proinflammatory mediator that is concerned with the generation of systemic and local responses to infection and injury." (PMID 25396430, 2014). "IL-1β can be elevated immediately after the infection with virulent avian virus strains as demonstrated for reovirus or Marek infections and also as a consequence of bacterial and virus co-infections, likely contributing to exacerbating lesions." (PMID 24460592, 2014). "We analysed the expression profiles of these ferritin isoforms, which exhibited distinct differences across tissues as well as changes in response to infection by A. salmonicida and stimulation with IL-1β." (PMID 25078784, 2014). "In the NOD-like receptor signalling pathway (hsa04621) 10 genes (of a total of 57 pathway genes) were differentially expressed at 4 h post infection and five of them were upregulated more than 10-fold, encoding IL6, IL1B, BIRC3, CXCL1 and CXCL2." (PMID 23326599, 2013). "In keeping with this, a strong reduction in Hp worms was noted along the entire small intestine of IL-1β−/− mice at a late timepoint post-infection (day 40)." (PMID 23935505, 2013). "To investigate differential inflammatory responses associated with Lmo-InlA-mur-lux and Lmo-EGD-lux infections, we measured serum levels of IFN-γ, IL-10, TNF-α, IL-6, CCL2, IL-5 and IL-1β at 3 and 5 days p.i. using Luminex bead arrays." (PMID 23617550, 2013). "Repeated treatment with LPS or MSU throughout the first six weeks of infection resulted in down-regulation of splenic IL-1β mRNA levels in infected RAG−/− mice by week six p.i., similar to the down-regulation seen in infected wild type mice." (PMID 24130499, 2013). "Macrophages infected with mutants lacking sdhA gene trigger Aim2-dependent activation of caspase-1, secretion of IL-1β and pyroptosis, which is reversible by infection with genetically complemented bacteria." (PMID 24324933, 2013). "The attenuation of the activation by infection with a double mutant of TdhA and S (ΔtdhAS) was observed, but caspase-1 activation and IL-1β processing persisted, suggesting that additional bacterial stimulators are involved in caspase-1 activation." (PMID 23357873, 2013). "Given that DEFB4 expression levels are driven by IL-1β, the combined effects of 1,25D and infection on DEFB4 transcription are consistent with levels of IL-1β secretion induced in 1,25D-treated, infected macrophages." (PMID 23762029, 2013). "We also compared their response to identically treated bone marrow-derived macrophages (BMDMs), which have already been shown to produce IL-1β upon MVA infection." (PMID 23356675, 2013). "Experiments will be performed in the presence of LPS or IL-1β as these are likely to be factors stimulating proinflammatory cytokines, prostaglandins, and proteases in the context of infection-induced PTB." (PMID 23840918, 2013). "Previously, studies examining the lack of activation/active suppression of inflammation by Francisella have been primarily focused on a limited set of well-known mediators, such as TNFα, IL6, IL1β, etc, as a measurement of immune response to infection." (PMID 23690939, 2013).
infection (continued). "qRT-PCR results revealed significant (p<0.05) induction of IL-1β, IL-2, and IFNγ transcription, with the greatest induction observed upon infection with the chicken-origin isolate." (PMID 23521892, 2013). "In response to brain injury or infection, IL-1β is both expressed by and targeted to many different cell types within the brain, such as microglia, astrocytes, endothelial cells, infiltrating leukocytes, neurons and oligodendrocytes." (PMID 24086523, 2013). "Taking mock-infected fish as a reference, expression of several cytokines (IFN-γ2, IL-1β, IL-6, and IL-10) was up-regulated as early as day 3 post-infection." (PMID 23865540, 2013). "IL-1β is also of critical importance during the early stages of infection as shown by in vitro infections using macrophages from these knockout mice." (PMID 23762029, 2013). "Among these cytokines, IL-1β is considered the primary regulator of the systemic response to infection." (PMID 24349401, 2013). "IL-1β−/− mice exhibited increased numbers of intestinal granulomas at both early and late timepoints following infection." (PMID 23935505, 2013). "We also observed a marginal increase in IL-1β release from Atg5-knockdown BMMs compared with that from control cells after infection with ΔtdhASΔvopQ." (PMID 23357873, 2013). "Lung IFNγ levels were highly elevated in mice deficient for both IL-1α and IL-1β or for IL-1R1 at 5 weeks after M. tuberculosis infection, reminiscent of TNF deficient mice at 4 weeks, when they succumb to infection." (PMID 25400917, 2013). "Co-culture significantly prolonged survival of infected macrophages, and 1,25D/infection-induced IL-1β secretion from macrophages reduced mycobacterial burden by stimulating the anti-mycobacterial capacity of co-cultured lung epithelial cells." (PMID 23762029, 2013). "The differential effect on BMDC IL-12 family with minimal effect on IL-10 and IL-1β expression during infection with the two WT strains was a surprising finding." (PMID 23922820, 2013). "This provides an important insight into the role of macrophages and the balance of IL-1β in managing the infection." (PMID 24312491, 2013). "Maximum secretion was observed at 1 day (24 h) after RV14 infection for IL-6 and IL-8 and at 3 days (72 h) after infection for IL-1β." (PMID 24303127, 2013). "Bone marrow-derived microglia shown here highly express the pro-inflammatory cytokine IL-1β, which has been reported to be a key mediator in the alteration of synaptic signal transmission during injury, infection and diseases of the CNS." (PMID 24303068, 2013). "To address this issue, we first examined IL-1β mRNA levels during pre-patent infection of wild type mice." (PMID 24130499, 2013). "To further confirm that the effect of YopK in vivo was not due to inhibition of the inflammasome or secretion of pro-inflammatory cytokines, we measured production of MCP-1 and IL-1β following infection of macrophages in vitro." (PMID 23633954, 2013). "IL-1β acts to decrease production of IL-25 and IL-33 at early time points following infection and parasite rejection was determined to require IL-25." (PMID 23935505, 2013). "MVA lacking IL-1β blocking activity leads to increased concentrations of free IL-1β upon infection of murine and human antigen presenting cells; this is likely responsible for enhanced memory T cell activation upon MVAΔIL-1βR immunization of mice." (PMID 23356675, 2013). "The immune response was quite different to that at the beginning of infection, with a prominent induction of IL1B gene expression, affecting pathways of MAPK signalling, and genes connected with cytokine-cytokine interactions and apoptosis." (PMID 23326599, 2013). "Mediating the recruitment of additional immune cells to the site of infection remains their most important task and members include ligands of the interleukin-1 (IL-1) family such as IL-1β and tumor necrosis factor-α (TNF-α)." (PMID 23971044, 2013).
infection (continued). "Infection with strains R20291 and 630 also mediated significant IL-1β secretion in the ex-vivo model of infection." (PMID 23922820, 2013). "IL-1β has long been recognized as a key mediator of immune and inflammatory responses during infection." (PMID 24146816, 2013). "Interleukin-1 (IL-1) family members, such as IL-1α, IL-1β, IL-1ra, and IL-18, are produced by various cells, such as lymphocytes, in response to inflammation produced by infection and microbial endotoxins." (PMID 23533315, 2013). "Mice were euthanized at 4 h, 24 h and 10 days after infection, and bacterial numbers, lung levels of inflammatory leukocytes, and lung expression of mRNA for inflammatory cytokines TNFα, IL-1β and mKC (IL-8 analogue) were evaluated." (PMID 23593362, 2013). "For instance, P. brasiliensis can trigger pro-IL-1β production in both bone marrow-derived cell types, but infection resulted in IL-1β maturation and release only in BMDCs." (PMID 24340123, 2013). "IL-25 deficient mice exhibited increased worm burdens at late time-points post-infection, indicating that even in the presence of normal IL-1β signaling low levels of IL-25 have a critical role in mediating worm expulsion." (PMID 23935505, 2013). "In our recent study, we observed the differential responses of M-Mφ and GM-Mφ to DV, such as infection rate, and the potential ability for IL-1β and IL-18 production." (PMID 23742038, 2013). "In contrast the expression of IL1B and IL18 was more substantially increased, with significant fold changes in expression of IL-1β mRNA (∼20-fold, p < 0.05) and IL-18 mRNA (∼30-fold, p < 0.05) at 120 min post-infection." (PMID 24137162, 2013). "This was consistent with the observation that cells from these animals secreted reduced amounts of IL-1β following infection with Salmonella or TLR7 stimulation." (PMID 24137163, 2013). "Both processes have been shown to contribute to control of infection in vivo, although recent data argues that neutrophils, instead of macrophages, are the main source of IL-1β in infected mouse." (PMID 24324933, 2013). "In this study, we found that murine bone marrow-derived dendritic cells responded to P. brasiliensis yeast cells infection by releasing IL-1β in a spleen tyrosine kinase (Syk), caspase-1 and NOD-like receptor (NLR) family member NLRP3 dependent manner." (PMID 24340123, 2013). "Previously we had reported that infection of GEC with P. gingivalis leads to expression of pro-IL-1β and its accumulation within the infected cell." (PMID 23936165, 2013). "Of note, IL-1β and IL-6 levels were consistently higher 8 h post infection in mice passively immunized with 2A3 compared to animals infected with Δhla." (PMID 24098366, 2013). "The manipulation of autophagy by pharmacological or genetic means has a profound impact on IL-1β production and secretion during infection or LPS treatment." (PMID 24273538, 2013). "Here we demonstrated that IL-1β production was required for effective macrophage responses to C. rodentium, and that excessive extraneous IL-1β in WT mice was deleterious, and exacerbated the infection." (PMID 24312491, 2013). "The production of IL-1β during the infection with Mycobacterium tuberculosis (Mtb) is important for successful host immune defense." (PMID 24130966, 2013). "Caspase-1 activation and IL-1β processing were markedly attenuated after infection with the TdhA mutant (ΔtdhA)." (PMID 23357873, 2013). "In vitro, murine myeloid dendritic cells, and activated, but not naive primary macrophages were identified as potent producers of IL-1β upon infection with MVA." (PMID 23356675, 2013). "In our study secretion of TNF-α and IL-1β were also positively correlated with IL-6 in addition to IL-12, after 24 hours of infection." (PMID 23667550, 2013). "Myeloid dendritic cells (mDCs) are potent antigen presenting cells and important for T cell priming; we therefore investigated their ability to respond to MVA infection by producing IL-1β." (PMID 23356675, 2013).
infection (continued). "The Yersinia pestis TIR-containing protein YpTdp interacts with MyD88 to reduce IL-1β- and LPS-dependent signaling and to contribute to modulation of cytokine secretion during infection." (PMID 23847770, 2013). "TLR activation signals through the NF-κB pathway to up-regulate the transcription of proinflammatory cytokines, including IL-1β, TNFα, and IL-6, which are essential for the recruitment of leukocytes to the lung and clearance of the infection." (PMID 23577168, 2013). "Mice passively immunized with anti-AT IgG prior to intranasal infection with S. aureus exhibited reduced IL-1β secretion and increased IFN-γ production in sera, leading to reduced PMN infiltration, improved lung pathology and ultimately survival." (PMID 24098366, 2013). "Further studies, measuring the levels of IL-1β, gastrin, histamine and somatostatin after long term experimental infection, are necessary to obtain additional insights into the influence of H. heilmannii s.s. on gastric homeostasis." (PMID 23895283, 2013). "This is in agreement with earlier reports and can be explained by the observation that TNF-α and IL-1β are produced early after infection and are removed quickly from the circulation." (PMID 23717702, 2013). "In contrast, IL-1β production is usually analyzed within the first 24 h of infection and hence the current data in the literature on Mtb-inflammasome activation does not take the Mtb entry in the host cell cytosol into account." (PMID 24130966, 2013). "The cytokines expression profile between K. rhinoscleromatis and K. pneumoniae infections shows minor differences in expression of IL-1β, IL-6 and IL-17, when similar infection kinetics is used." (PMID 23554169, 2013). "Downstream of TNFα, IL-1β, and IL-6 other cytokines are released such as IL-8 that induce migration of neutrophils and phagocytes to the site of infection." (PMID 24391635, 2013). "Specifically, an oscillation pattern was observed in the temporal response of NF-κB activation, a feature similar to that observed in reporter cell lines following stimulation with TNF-α, LPS and IL-1β or infection with Helicobacter pylori." (PMID 23383093, 2013). "Cytokines such as TNF-α and IL-1β that are considered harmful to periodontal tissue in chronic inflammation play important roles in the control of pathogen infection in the acute inflammation." (PMID 23977160, 2013). "Here we noted that rUSSR-NS PR8 infection, which resulted in the highest IL-1β expression, produced the least tissue damage." (PMID 23592984, 2013). "The NLRP3 inflammasome is the most characterized inflammasome activated by cellular infection or stress, which is responsible for the maturation of proinflammatory cytokines IL-1β and IL-18." (PMID 23942110, 2013). "Another important pro-inflammatory cytokine induced during infections is IL-1β; its expression is induced by NF-κB transcription factors." (PMID 23358433, 2013). "NLRC4 plays a vital role in regulating IL-1β and IL-18 production during lung mucosal defense following infections with Pseudomonas aeruginosa and Burkholderia pseudomallei." (PMID 23577168, 2013). "It is noteworthy that IL-1 family cytokines, including IL-1β and IL-18, have adjuvant properties, as they can induce antigen-specific immune responses against infection." (PMID 24155747, 2013). "Aside from mediating immune response to pathogen infection, IL-1β and IL-18 play an important role in driving adaptive immunity during infection." (PMID 23742038, 2013). "For instance, macrophages released less IL-1β upon infection with transcription factor-deleted Δupc2 strain than wild-type C. albicans, although this mutant was competent in forming hyphae." (PMID 24205058, 2013). "Previous studies on the role of IL-1β in the innate immune response to infection have focused on its capacity to control infection by autocrine signaling from infected macrophages." (PMID 23762029, 2013).
infection (continued). "Caspase-1 activation and the processing/release of IL-1β upon infection with ΔtdhAS were partially but significantly enhanced by the knockdown of ATG5." (PMID 23357873, 2013). "Cathepsin B appears to be required for NLRP3 activation in response to infection with T. cruzi, as pharmacological inhibition of cathepsin B abrogates IL-1β secretion." (PMID 24098823, 2013). "We further focused on the role of 1,25D- and infection-induced interleukin 1β (IL-1β) expression in response to infection." (PMID 23762029, 2013). "We used RT-qPCR to investigate the level of expression of three cytokines characteristic of acute inflammation, TNFα, IL1β and mKC, a mouse analogue of human IL-8, at 24 h post infection." (PMID 23593362, 2013). "These responses, which are organized to fight against the infection, are triggered by proinflammatory cytokines such as interleukin (IL)-1β, tumor necrosis factor-alpha (TNF-α), and IL-6." (PMID 24349401, 2013). "Infection with recombinant rUSSR-NS1 1918 resulted in the lowest IL-1β levels in NHBE cells compared to infection with parental WT rUSSR, PR8, and rUSSR-NS PR8." (PMID 23592984, 2013). "At day 3, viral load was also similar in WT rUSSR- and rUSSR-NS1 1918-infected ferrets; yet rUSSR-NS1 1918 infection resulted in a significantly lower IL-1β response than WT rUSSR infection." (PMID 23592984, 2013). "Compared to infection with wild-type virus, mice infected with reverse engineered PB1-F2-deficient IAV resulted in decreased IL-1β secretion and cellular recruitment to the airways." (PMID 23737748, 2013). "Unprimed BMDMs secrete robust levels of IL-1α and IL-1β by 20 hours post-infection with wild-type L. pneumophila (WT Lp)." (PMID 23762026, 2013). "Salmonella enterica serovar Enteritidis TlpA is capable of reducing NF-κB activation by TLR4, IL-1R and MyD88-dependent pathways and to contribute to control of IL-1β secretion during infection." (PMID 23847770, 2013). "It is of particular importance for IL-1β secretion from macrophages after infection with Mycobacteria marinum (M. marinum) and Mtb." (PMID 23762029, 2013). "In the event of intra-amniotic infection or choriodecidual space infection, inflammatory cytokines such as IL-1α, IL-1β, IL-6, IL-8, and granulocyte colony-stimulating factor are released." (PMID 23818902, 2013). "Supernatants from THP-1 cells infected with MVAΔIL-1βR stimulated the highest levels of reporter gene expression, demonstrating that more biologically active free IL-1β was available than in other infections or THP-1 mock controls (left block)." (PMID 23356675, 2013). "To confirm the contribution of epithelial signaling by infection- and 1,25D-induced IL-1β towards the reduction in mycobacterial burden, we knocked down IL1R1 receptor expression in SAECs 36 hours prior to their co-culture." (PMID 23762029, 2013). "Our results showing that type I IFN controls inflammasome activation and production of bioactive IL-1β add to our knowledge of how airway epithelial cells respond to infection and regulate lung innate and adaptive immunity." (PMID 23592984, 2013). "In our study, the serum level of IL-1RA was elevated in children with acute urticaria and evidence of infection, likely representing a protective response to rise of IL-1β." (PMID 24490166, 2013). "These caspases were originally identified for their role in IL-1β processing and release but are now known to direct additional important cellular processes during infection, inflammatory disorders, and response to injury." (PMID 24367258, 2013). "Inflammatory cytokines, including TNF-α, IL-1β and IL-6, can be released by activation of mononuclear macrophages after severe trauma, infection and shock." (PMID 24039865, 2013). "IL-1β was detected 4 hours after infection, and was still increasing up to 24 hours after infection." (PMID 23356675, 2013).